KLF2 (KLF transcription factor 2)
Diseases named in the same sentence as KLF2 in open-access papers (continued):
Sharing a sentence is not in itself a finding about the gene and the disease.
tumor (continued). "New clonotypes appearing in blood or tumor at disease progression were enriched for genes associated with cytotoxicity or stemness (FGFBP2, GNLY, GZMH, GZMK, IL7R, SELL and KLF2), and these might be harnessed for alternative cellular therapy or cytokine therapy." (PMID 36514045, 2022). "In addition to regulation of myeloid cell activation and various inflammatory diseases, role of KLF2 is also emerging as a potential tumor suppressor gene owing to its roles in the inhibition of proliferation, migration and angiogenesis and in the induction of apoptosis, senescence and adhesion." (PMID 29125549, 2017). "It was reported that KLF2 could inhibit tumor cell proliferation mediated by KRAS." (PMID 28938648, 2017). "Moreover, previous study showed that EZH2 could directly bind to KLF2 promoterto silence KLF2 expression, resulting in the block of the tumor-suppressor features of KLF2." (PMID 28938648, 2017). "Moreover, there is evidence showed that EZH2 could directly bind to KLF2 promoter and silence of KLF2 expression result in blocking the tumor-suppressor features of KLF2, which is partly mediated by p21." (PMID 26336870, 2015). "Only advanced-stage EOCs appeared to be characterized by a scenario that involves genes such as FPR1, KLF2 and THBD, to date associated with thrombosis and cardiovascular disease, thus suggesting that this pathway contributes to the growth and/or the spread of this type of tumor." (PMID 23889749, 2013). "Two CD103+ resident (CD69+, CD103+, KLF2−) T cell clusters were identified and denoted as TEX and TRM populations with TEX cells mostly present in tumor-derived tissue and TRM clusters present in both tumor and noncancerous tissue." (PMID 41461987, 2026). "For instance, TRAF7 (cg02678414) acts as a tumor suppressor, and its restoration inhibits AML proliferation via the KLF2-PFKFB3 glycolytic pathway." (PMID 40730747, 2025). "PRDX2, PKD2 (polycystin-2), and AQP1 were overexpressed in tumor tissues, whereas SOD3 and KLF2 were downregulated." (PMID 41140697, 2025). "Violin plots demonstrated significantly elevated activities of IRF5, IRF8, KLF2, TFAP2B, and MAFK in Zbp1−/− tumor cells, while E2F4 and ETV4 were preferentially activated in WT tumors." (PMID 41430036, 2025). "Under hypoxic conditions, miR-182-5p directly inhibits Krueppel-Like Factor 2 (KLF2) and KLF4 and induces an accumulation of Vascular Endothelial Growth Factor Receptor (VEGFR) with the consequent promotion of tumor proliferation and angiogenesis." (PMID 39684236, 2024). "The results indicated that in MTC, PTC, and ATC tumor tissues, DCs exhibited the lowest co-stimulatory function scores in MTC and the highest expression levels of KLF2." (PMID 39030177, 2024). "Kruppel like factor 2 (KLF2) correlates to the expression of GPX4 in ccRCC and overexpressed KLF2 inhibits tumor growth and invasion by regulating ferroptosis." (PMID 38095762, 2024). "In the embryonic stem cell subnucleus, KLF2 and KLF4 co-localize with OCT4, and KLF-DNA binding dynamics occur during differentiation for direct regulation of stem cell genes and tumor neovascularization." (PMID 38560274, 2024). "The overexpression of KLF2 affected WNT5A, WNT5B, and FZD-2 in the WNT signaling pathway, which regulates epithelial-mesenchymal transition involved in tumor metastasis." (PMID 36761967, 2023). "The expression of fibrotic genes EGR1, JUND, KLF2 and TAGLN also decreases in tumour samples (PH4 module)." (PMID 38157373, 2023). "Previous studies reported KLF2 promote cell proliferation and ETS1 and ETS2 contribute to angiogenesis, indicating tumor-promoting functions of these tumor-derived clusters." (PMID 37644609, 2023). "lower in various tumor tissues than in normal tissues through the TIMER2.0 database, and KLF2 mRNA expression was significantly lower in STAD tissues than in normal tissues." (PMID 36874616, 2023).
tumor (continued). "It has been reported that exosomal miR-25-3p from CRC cells promotes vascular leakiness, vascular permeability, and angiogenesis via targeting KLF2 and KLF4 to enhance tumor metastasis." (PMID 36793126, 2023). "AGAP2-AS1 is involved in cell migration and promotes tumorigenesis by suppressing the tumor suppressors LATS2 and KLF2." (PMID 37531393, 2023). "On the other hand, ncRNAs can promote the tumor cell growth and proliferation by PRC2 mediated KLF2 targeting." (PMID 37807067, 2023). "KLF2 knockdown in leukemic cells can restrict growth inhibition by UM171, supporting a tumor suppressor function for this transcription factor." (PMID 36335089, 2022). "LKLF (or KLF2) is a zinc finger-containing transcription factor that plays a negative regulatory role in cytotoxic T-lymphocyte (CTL), killing tumor cells by blocking the mimicry of IL2, tumor necrosis factor (TNF)-α, and interferon (IFN)-γ." (PMID 36341370, 2022). "The expression of HMGB1 and TLR4 was significantly high in tumor tissue compared with that in normal tissue, the expression of CCL28, KLF2 and TNFSF18 in tumor were similar to normal tissues." (PMID 36204682, 2022). "An enhancement of miR‐126‐5p and KLF2 while reductions in EZH2 and BIRC5 were seen in tumour tissues of nude mice treated with X‐ray alone or combined with lv‐miR‐126‐5p." (PMID 35322532, 2022). "The differential expression in GRNs identified in each patient also confirmed the tumor heterogeneity of SBA, with transcription factors (TFs) such as BATF, CREB3L1, KLF2, E2F1 variably expressed among different patients." (PMID 36104333, 2022). "The Hub gene was identified and constructed based on 6 genes (KLRB1, KLF2, S100A9,MSC,ANXA5 and IMPDH1), which will help to for a predictive analysis of the tumor immune microenvironment in HCC patients." (PMID 35992798, 2022). "KLF2 belongs to the KLF family, a subclass family of zinc-finger-containing transcription factors characterized by a DNA-binding domain, and modulates tumor proliferation, apoptosis, metastasis, and microenvironment." (PMID 34257272, 2021). "Critically, a recent study authenticates that lncRNA ZnF503-AS1 recruits transcription factor GATA6 and thus exerts its tumor-suppressive function and lncRNA TUG1 enhances cell growth and apoptosis by epigenetically silencing of transcription factor KLF2." (PMID 34858502, 2021). "Our results support that KLF2 is a target of miR-BART17-5p and acts as a tumor suppressor in EBVaGC." (PMID 32075248, 2020). "Published studies indicated that ZFAS1 directly repressed KLF2 and NKD2 expression to promote tumor cell proliferation, and induced ZEB1 to enhance the epithelial–mesenchymal transition (EMT) and metastatic ability." (PMID 29678899, 2018). "In the current study, our findings showed that KLF2 and LATS2 functioned as a tumor suppressor in CCA." (PMID 29642935, 2018). "LSD1 was recruited to Kruppel-like factor 2 (KLF2) or E-cadherin promoters via binding with several lncRNAs in NSCLC cells, resulting in promoted tumor proliferation and EMTs." (PMID 30002791, 2018). "In this study, we found that KLF2 also functions as tumor suppressors in CRC cells and knockdown of KLF2 is involved in the LL22NC03-N64E9.1-exerted oncogenic function in CRC cells." (PMID 28938648, 2017). "Here, we showed for the first time that AGAP2-AS1 exerted oncogenic functions in human NSCLC cells by suppression of tumor suppressors LATS2 and KLF2." (PMID 27195672, 2016). "KLF2, an member of KLF family with Cys2/His2 zinc-finger domains, is diminished in multiple cancers and possesses tumor-suppressor features such as inhibition of cell proliferation mediated by KRAS." (PMID 26840083, 2016).
tumor (continued). "FBW7 exerts its anti-tumor activity by targeting a ever-growing list of ubiquitin substrates including MED13, KLF2, and Mcl-1." (PMID 24899581, 2014). "Notably, significant correlations were observed only between plasma cells and KLF2-expressing tumor cells, but not between plasma cells and KLF2-expressing non-tumor cells, suggesting that KLF2-expressing tumor cells may be associated with plasma cell recruitment in diffuse-type GC." (PMID 40075643, 2025). "In both models, systemic administration of 4-1BB antibody targeted KLF2 (+4-1BB-KLF2), but not 4-1BB targeted control (+4-1BB-Ctrl), siRNA enhanced vaccine-induce antitumor immunity, measured as tumor progression and survival." (PMID 40162209, 2025). "Here we show that experimental downregulation of KLF2 in vaccine activated CD8+ T cells led to the accumulation of intratumoral phenotypically defined CD69+CD103+ and CD69+CD49a+ Trm, which correlated with enhanced inhibition of tumor growth." (PMID 40162209, 2025). "In tumor cells, although the promoter remained accessible and RNA Pol II was present, the transcription was paused, as demonstrated by the lack of KLF2 transcripts in RNA-seq and GRO-seq analyses." (PMID 39796183, 2025). "Differential gene expression analysis revealed that tumor-infiltrating γδ T cells, regardless of subtype, exhibited higher expression of KLF2 and GZMB." (PMID 39454432, 2024). "We observed a downward trend in KLF2 expression with the increase of pathological grade and pathological stage, and KLF2 expression exhibited a negative correlation with tumor size, lymph node metastases, and distant metastasis." (PMID 37123417, 2023). "KLF2 and KLF4 possess anti-inflammatory effects but also impact macrophage proliferation, differentiation, activation, and tumor growth inhibition, demonstrating their dual nature in tumor immunity." (PMID 37533434, 2023). "In vivo studies show that the overexpression of CDK8 has negative results on KLF2 expression and leads to an increase in tumor size and the presentation of endothelial markers." (PMID 37239940, 2023). "KLF2 can inhibit the transcriptional activity of SMAD2/3 and SMAD4 in the TGF-β/SMAD pathway, improving TGF-β-induced target gene expression and inhibiting tumor growth and migration in HCC." (PMID 36761967, 2023). "Altruistic cells persist in the tumor despite their self-sacrifice, as they can regenerate epigenetically from non-altruists via a KLF2/PCAF-mediated mechanism." (PMID 38093346, 2023). "Krüppel-like factor 2 (KLF2) is an important member of the KLF family, a subclass of zinc-finger-containing transcription factors with DNA-binding domains, which can regulate tumor proliferation, metastasis, and affect the microenvironment." (PMID 36619866, 2022). "The results of this study showed that KLF2 protein exerts tumor suppressor ability in HCC by the negative feedback pathway of TGF-β signaling." (PMID 35992798, 2022). "In pancreatic cancer, DUXAP8 promotes tumor growth through epigenetic silencing of CDKN1A and KLF2." (PMID 34957112, 2021). "Statistical data were presented in histograms (KLF2(total)/DAPI area ratio: PBS, 0.027 ± 0.0034; EXO, 0.012 ± 0.0055; KLF2(tumor)/DAPI area ratio: PBS, 0.023 ± 0.0025, EXO, 0.011 ± 0.0052; KLF2(vessel)/CD31 area ratio: PBS, 0.026 ± 0.012, EXO, 0.0049 ± 0.0026, *P < 0.05, **P < 0.01)." (PMID 34257272, 2021). "Next, we selected several EZH2 or LSD1 potential targets (P15, P21, KLF2, PTEN, KLF2, LATS2, RND3, and NKD2) with tumor-suppressive role, and hypothesized that some of which might be associated with LINC00665-mediated carcinogenicity." (PMID 34094920, 2021). "By contrast, KLF2, KLF4 and KLF6 are more likely tumor suppressors in different cancers." (PMID 32523679, 2020). "KLF2, a member of the KLF family, acts as a tumor suppressor in many cancers." (PMID 32075248, 2020).
tumor (continued). "Next, we selected several EZH2 or LSD1 potential targets (P15, P21, KLF2, PTEN, TFPI2, LATS2, E-cadherin, and RND3) with tumor-suppressive role, and hypothesized that some of which may be associated with AGAP2-AS1-mediated carcinogenicity." (PMID 31186379, 2019). "Next, we selected several EZH2, LSD1 or DNMT1 potential targets (P15, P21, LATS2, RND1, KLF2, NKD2, PTEN) with tumor-suppressor function and SPRY4, and hypothesized that they may involve in the contributions of SPRY4-IT1 to CCA progression." (PMID 29642935, 2018). "KLF2, a key member of the Kruppel-like factor (KLF) family that with Cys2/His2 zinc-finger domains, which is reported to exert tumor suppressor functions in many malignancies, but its functional role in CRC remains unclear." (PMID 28938648, 2017). "KLF2, a member of the Kruppel-like factor (KLF) family, also exerts tumor-suppressive roles." (PMID 29137412, 2017). "Taken together, our findings indicate that AGAP2-AS1 may act as an oncogene by repressing tumor-suppressor LATS2 and KLF2 transcription." (PMID 27195672, 2016). "Furthermore, we determined that knockdown of AGAP2-AS1-mediated tumor-suppressive effects on NSCLC cells are partly dependent on regulation of LATS2 and KLF2 expression." (PMID 27195672, 2016). "In addition, KLF2 and KLF6 significantly reduced VEGFR2 expression to inhibit tumor angiogenesis." (PMID 36761967, 2023). "KLF2 acts as a tumor suppressor in CRC via regulating HIF-1α/Notch-1 signaling pathway." (PMID 32523679, 2020). "Here, we reported that DUXAP10 could not only repress tumor suppressors LATS1 and KLF2 transcription through epigenetic modification by interacting with PRC2 and LSD1, also can regulate β-catenin mRNA stability by recruiting RNA binding protein HuR at post-transcriptional level in GC cells." (PMID 29374493, 2018). "Furthermore, we chose several EZH2 or LSD1 potential targets (P15, P21, LATS1, LATS2, RND1, KLF2, E-cadherin, PTEN, ASPP2 and RRAD) with tumor-suppressor function, and hypothesized that they may involve in the contributions of AGAP2-AS1 to NSCLC progression." (PMID 27195672, 2016). "Here we propose that NK-like cells expressed the transcription factors KLF2, KLF3, and MYBL1, which have been also reported as features of cytotoxic, non-dysfunctional subsets in tumours infiltrating T cells." (PMID 38012187, 2023). "DP T cells expressed ITGAE (codes for CD103), and CD69, but not SELL, KLF2, and S1PR1, suggesting a tumor resident phenotype." (PMID 30534127, 2018). "Although Klf2 was reported to be one of the KLF family proteins the expression of which in vascular endothelium was induced by SS, its expression was not increased in circulating GFP+ tumor cells in the present study." (PMID 30651129, 2019). "However, the changing expression of KLF2 and NOTCH2 during tumor progression has not been delineated." (PMID 28887496, 2017).
cancer (64 papers, 2010 to 2026). A tumor composed of atypical neoplastic, often pleomorphic cells that invade other tissues. "Aberrant expression of KLF2 has been reported in a variety of cancers; however, the association and the role of KLF2 and GC have not been elucidated." (PMID 36874616, 2023). "33-genes related with cancer associated fibroblasts (CAFs) were collected to identify the significant association of KLF2 with fibrosis." (PMID 37386390, 2023). "Results showed that the CAFs-related target gene, SPP1, is a key regulatory gene of KLF2 affecting cancer fibrosis, and is also a promising diagnostic factor for HCC." (PMID 37386390, 2023). "The downregulation of KLF2 expression is closely associated with the heightened proliferation and invasive capabilities observed in various types of cancer." (PMID 38149239, 2023). "A recent study showed that downregulation of KLF2 expression in human cancers is caused by epigenetic silencing of histone methyltransferase EZH2." (PMID 36874616, 2023). "This review is an effective step towards introducing the KLF2 as a suitable diagnostic and therapeutic target in cancer patients." (PMID 37807067, 2023). "We observed increased plasma cell proportions in diffuse-type tumors associated with epithelial-resident KLF2 and stage-wise accrual of cancer-associated fibroblast subpopulations marked by high INHBA and FAP coexpression." (PMID 34642171, 2022). "Indeed, further animal studies and clinical trials are needed to be able to use the lncRNAs/PRC2/KLF2 axis for diagnostic and therapeutic purposes in cancer patients." (PMID 37807067, 2023). "Therefore, we further studied the association between cancer associated fibroblasts (CAFs) and KLF2." (PMID 37386390, 2023). "Therefore, KLF2 and its ncRNA regulators can be introduced as appropriate therapeutic and diagnostic targets in cancer patients." (PMID 37807067, 2023). "Besides the therapeutic importance, lncRNAs/PRC2/KLF2 axis can also be used as a diagnostic/prognostic marker in cancer patients." (PMID 37807067, 2023). "Since the transcription of miRNAs with anti-oncogenic activity is often regulated by TFs that are themselves oncosuppressors, we focused on EBF1, ETS2, and KLF2, which are frequently deregulated in cancer, and can bind to the EGFL7/miR-126 promoter regions." (PMID 39796183, 2025). "Our results provide a therapeutic means of targeting KLF2 to promote the expansion and long-term survival of NK cells and improve NK cell engraftment and sustainability in cancer patients." (PMID 39906661, 2024). "We employed bioinformatics tools and online websites to investigate the differential expression of KLF2 in pan-cancer." (PMID 37123417, 2023). "Further experimental analysis of HCC samples exhibited that the expression levels of KLF2 and ANXA5 were associated with immune cell infiltration and expression of PD-L1 in cancer tissues." (PMID 35992798, 2022). "Intriguingly, mounting evidence has demonstrated the regulatory relationship between EZH2 and KLF2 in a variety of cancers." (PMID 34462420, 2021). "Cancer cells exhibited epigenetic silencing of KLF2 through direct transcriptional repression mediated through the EZH2–H3K27me3 axis." (PMID 34685528, 2021). "Otherwise, we have proposed a new role of TIMP2/KLF2 in the formation of cancer-induced pre-metastatic niche, and provided new insights into the formation of the metastasis niche." (PMID 34497265, 2021). "Relevant to our context is the notion that KLF2 is important for Tregs production, immune cells that in malignancies help cancer cells to evade treatment response." (PMID 33250051, 2020).